EGFR (epidermal growth factor receptor)
Diseases named in the same sentence as EGFR in open-access papers (continued):
Sharing a sentence is not in itself a finding about the gene and the disease.
colorectal cancer (continued). "Previous studies already suggested that EGFR played an important role in angiogenesis of early tumor, which is associated with the progression of colorectal carcinoma, and is a widely used prognostic factor." (PMID 27888614, 2017). "The progression of colorectal cancer (CRC) involves recurrent amplifications/mutations in the epidermal growth factor receptor (EGFR) and downstream signal transducers of the Ras pathway, KRAS and BRAF." (PMID 27562229, 2016). "An increased EGFR copy number is associated with a favorable response to anti-EGFR therapy in patients with KRAS wild-type colorectal cancer." (PMID 27014419, 2016). "K-RAS mutations are one of the biological determinants of anti-EGFR target therapy resistance in colorectal cancer." (PMID 26868125, 2016). "In KRAS mutated colorectal cancer cells, which are resistant to anti-EGFR therapy, combining of terpinen-4-ol with cetuximab (1 μM) resulted in impressive efficacy of 80–90% growth inhibition." (PMID 27275783, 2016). "The EGFR polymorphism (rs2227983) observed in this patient is associated with increased survival of colorectal cancer patients treated with Cetuximab27,28, perhaps via attenuation of EGFR pathway signaling." (PMID 27723755, 2016). "Anti-EGFR targeted therapy is of increasing importance in advanced colorectal cancer and prior KRAS mutation testing is mandatory for therapy." (PMID 27064574, 2016). "KRAS mutations are responsible for resistance to anti-epidermal growth factor receptor (EGFR) therapy in colorectal cancer patients." (PMID 27043547, 2016). "Resistance to EGFR inhibitors, which are among the most commonly used targeted therapies for colorectal cancer, occurs with mutations in EGFR-related molecules." (PMID 27090874, 2016). "Network analysis of the PTPN1 gene associations in colorectal cancer shows links with several oncogenes such as EGFR, STATs, and Src." (PMID 26942883, 2016). "Development of colorectal cancer (CRC) associates with accumulation of genetic mutations include the epidermal growth factor receptor (EGFR) signaling pathway." (PMID 27074743, 2016). "Since the advent of monoclonal antibodies against epidermal growth factor receptor (EGFR) in colorectal cancer therapy, the determination of RAS mutational status is needed for therapeutic decision-making." (PMID 27685259, 2016). "Targeted next generation sequencing (tNGS) has become part of molecular pathology diagnostics for determining RAS mutation status in colorectal cancer (CRC) patients as predictive tool for decision on EGFR-targeted therapy." (PMID 27756406, 2016). "Colorectal cancers (CRC) frequently overexpress epidermal growth factor receptor (EGFR), which is associated with tumor progression and poor prognosis." (PMID 26569500, 2015). "Our previous study in colorectal cancer cell lines revealed that the KRAS G12D mutation decreased the impact of CIP2A on downstream effectors of the EGFR signaling pathway, when cells were treated with temsirolimus." (PMID 25896895, 2015). "The detected c.146A>T variant is known from colorectal cancer and leads to EGFR-therapy resistance in this entity." (PMID 25894969, 2015). "In colorectal cancer EGFR is rarely mutated, while gene amplification is more frequent and associates to a better response to anti EGFR monoclonal antibodies." (PMID 25987127, 2015). "For instance, the KRAS gene mutated exclusively with the PTEN, VHL, RB1, and EGFR genes in large intestine cancers with high statistical significance." (PMID 26212640, 2015). "Mutations in BRAF are known to negatively impact anti-EGFR therapy in colorectal cancer but have a beneficial effect in melanoma in response to the use of BRAF/MEK inhibitors." (PMID 26315110, 2015). "Studies suggest that epidermal growth factor receptor (EGFR) signaling activation is a causal driver of many stem cell-derived epithelial cancers, including colorectal cancer." (PMID 26683696, 2015).
colorectal cancer (continued). "The clinical utility of EGFR expression detection by IHC in colorectal cancer is still somewhat inconclusive, with numerous studies failing to demonstrate a predictive and/or prognostic role for EGFR IHC as a companion diagnostic test for cetuximab." (PMID 26149458, 2015). "Currently also mutations at exon 20 of PIK3CA, although rarely found in colorectal cancer patients (less than 5% in most studies) have been demonstrated to determine resistance to anti-EGFR monoclonal antibodies." (PMID 25943333, 2015). "For example, the KRAS mutation status in colorectal cancer is related to the effectiveness of anti-epidermal growth factor receptor (EGFR) antibodies." (PMID 26046304, 2015). "Of the 13 patients for whom KRAS sequencing was performed, 4 patients (30.8%) had wild-type KRAS, which is associated with response to anti-EGFR therapy in colorectal cancer." (PMID 26161408, 2015). "Until recently, indications for standard-of-care molecular testing in colorectal carcinomas included testing for KRAS mutational status as a predictor of response to anti–epidermal growth factor receptor (EGFR) agents such as cetuximab." (PMID 26366557, 2015). "Epidermal growth factor (EGF) receptor (EGFR) and associated signal transduction pathways have emerged as important molecular therapeutic targets for colorectal cancer." (PMID 24618737, 2014). "The absence of both KRAS and BRAF mutations are common features seen in colorectal cancers that are responsive to cetuximab, thus making the EGFR mutation in this case of particular interest." (PMID 24894453, 2014). "Acquired KRAS mutations have also been implicated as a mechanism of resistance after anti-EGFR targeted therapy in colorectal cancer." (PMID 25119929, 2014). "Among the most important members of the family is KRAS, which is mutated in over 30% of colorectal cancers and predicts poor response to anti-EGFR therapy." (PMID 24874471, 2014). "In another study involving 102 advanced colorectal cancer patients, 75.5% of the cases were found to express EGFR, which was significantly associated with disease relapse." (PMID 24609222, 2014). "Genetic mutations that lead to EGFR overexpression were associated with cancer, mainly lung and colorectal cancer." (PMID 25713610, 2014). "While EGFR mutation has historically been believed to be rare in colorectal carcinomas, whole exome sequencing published through The Cancer Genome Atlas identified somatic non-synonymous coding EGFR mutations in 10 of 224 colorectal carcinoma cases (or 4.5%)." (PMID 24894453, 2014). "As a proof-of-concept we developed and validated a multiplexed in situ assay for the activating point mutations in KRAS codon 12 and 13 that are associated with resistance to anti-EGFR therapy in colorectal cancer." (PMID 24280411, 2013). "The apparent discrepancies between the results of our present study and those previously reported can be explained as follows: First, EGFR is expressed in 40%–70% of colorectal cancers, and evidence suggests an association with survival." (PMID 23824671, 2013). "EGFR is overexpressed in up to 80 % of colorectal cancers and is associated with a poor survival outcome." (PMID 23921573, 2013). "Further studies are necessary to better understand the association between TATI/SPINK1 and EGFR in colorectal cancer and for evaluating the potential use of this marker combination to predict treatment response." (PMID 24204699, 2013). "Tumour growth in colorectal cancer and other solid cancers is frequently supported by activating mutations in the epidermal growth factor receptor (EGFR) signaling pathway (Patholog Res Int 2011:932932, 2011)." (PMID 24152305, 2013). "In contrast to colorectal cancer, mutations within the EGFR in NSCLC are common and mutational testing is recommended for all NSCLC cases." (PMID 24199171, 2013). "Colorectal cancer patients with activating RAS mutations are resistant to EGFR inhibitors such as Cetuximab." (PMID 23335975, 2013).
colorectal cancer (continued). "Activating KRAS and BRAF mutations predict unresponsiveness to EGFR-targeting therapies in colorectal cancer (CRC), but their prognostic value needs further validation." (PMID 24020794, 2013). "Each laboratory using one or more genotyping method was evaluated by an external quality control program, the multicenter program: KRASOncogene Mutation detection in the treatment of Metastastic Colorectal cancer by EGFR Antibodies (MOKAECM)." (PMID 23935912, 2013). "Again, the germline silent mutation in EGFR exon 20 aa787 was returned from the analysis in all colorectal carcinoma samples in this study and has been reported by others." (PMID 23922754, 2013). "In terms of therapy KRAS mutational status has been linked to EGFR inhibitor resistance in colorectal cancer, but further studies are needed in endometrial carcinoma to explore such potential link." (PMID 23300780, 2012). "In colorectal cancer, the efficacy of both monoclonal antibodies against EGFR, cetuximab and panitumumab, is dependent upon the mutational status of KRAS." (PMID 23198146, 2012). "In colorectal cancer, high polysomy or amplification of EGFR was associated with response to cetuximab therapy, whereas loss of PTEN expression, (evaluated by IHC) rather is indicative for therapy resistance." (PMID 22240798, 2012). "Similar to KRAS mutations, EGFR overexpression has also been linked to poor prognosis and increased risk of metastasis in colorectal cancer and, therefore, represents a promising therapeutic target." (PMID 23202889, 2012). "Inhibition of epidermal growth factor receptor (EGFR) in colorectal cancer was used to investigate potential causes for low predictive values of many preclinical studies." (PMID 22761823, 2012). "Increased copy number of the EGFR gene is associated with response to cetuximab in colorectal cancer patients." (PMID 22152101, 2011). "Most of colorectal cancer(CRC) is characterized with overexpression of epidermal growth factor receptor(EGFR) and predicted with high risk of metastasis and recurrence." (PMID 21464950, 2011). "Of note, KRAS-G12D has a high prevalence (35%); this cancer driver mutation is present in 40% of colorectal cancers and is associated with anti-EGFR therapy resistance." (PMID 22185227, 2011). "There is another paper in this series, “Impact of KRas mutations on management of colorectal cancer” by Sullivan and Kozuch, which provides an in-depth review of the predictive value of KRas and other members of the EGFR signaling pathway." (PMID 21403829, 2011). "This cell line also harbors an activating KRAS G12V mutation, which is associated with resistance of colorectal cancers to the EGFR-directed therapy cetuximab." (PMID 21666749, 2011). "Response to EGFR-targeted therapies in colorectal cancer patients has been convincingly associated with Kirsten-Ras (K-Ras) mutation status." (PMID 20147967, 2010). "EGFR is overexpressed in a variety of solid tumors, including colorectal cancer (CRC), and its overexpression is associated with poorer prognosis." (PMID 20680104, 2010). "EGFR expression is implicated in the pathogenesis of colorectal cancer and a direct relationship between EGFR expression by colon cancer cells and their ability to produce hepatic metastasis has been shown in preclinical models." (PMID 19997103, 2010). "Other potential biomarkers of cetuximab activity in colorectal cancer include EGFR ligands (epiregulin and amphiregulin) and polymorphisms in EGFR, EGF, and Fc fragment of IgG receptor." (PMID 19127259, 2009). "KRAS mutations represent key alterations in colorectal cancer development and lead to constitutive EGFR signaling." (PMID 19832985, 2009). "Presence of KRAS mutations therefore represents a negative predictor of response to EGFR therapy and KRAS mutation testing has rapidly moved into the molecular diagnostic work-up of colorectal cancers considered for EGFR treatment." (PMID 19832985, 2009).
colorectal cancer (continued). "Since EGFR inhibition represents a therapeutic strategy in advanced colorectal cancer, KRAS mutation analysis has quickly been introduced as a treatment-predictive test." (PMID 19832985, 2009). "It is interesting that KRAS mutations were found in both cell lines (HuCCT1 and OZ) considered refractory to vandetanib in this study, and KRAS mutation has been reported as a mechanism of resistance to EGFR inhibitors in lung and colorectal cancers." (PMID 19319137, 2009). "For example, lung and colorectal cancers that harbor mutations in the KRAS oncogene are unresponsive to treatment with anti-EGFR agents, and inactivating PTEN mutations (or protein loss) in glioblastomas predict resistance to erlotinib." (PMID 19924296, 2009). "Colorectal cancer is frequently associated with high expression levels of EGFR (25–80%) resulting in a more aggressive disease and a poor prognosis." (PMID 18182978, 2008). "This study revealed that Id-1, EGFR and VEGF took part in development and progression of colorectal carcinomas and that Id-1 was associated with regulations of EGFR and VEGF." (PMID 19014499, 2008). "Compared with the EGFR coding sequences in the GenBank, which originated from A431 cells, no mutations were found in the tyrosine kinase domain of EGFR in DiFi colorectal carcinoma cells." (PMID 17931419, 2007). "The epidermal growth factor receptor (EGFR), which participates in signalling pathways that are deregulated in cancer cells, is frequently mutated in colorectal-cancer cells." (PMID 16508634, 2006). "Interleukin-4 receptor (IL-4R) and Epidermal Growth Factor receptor (EGFR) were assessed as factors associated with adenoma-carcinoma progression in colorectal cancer and tumour invasion." (PMID 1419612, 1992). "Given that HER2‐positive colorectal cancer, such as in this case, a rare subtype, accounts for 2%–3% of colorectal cancers, and is associated with a poor response to anti‐epidermal growth factor receptor antibody therapy, targeted treatment options must be considered." (PMID 40821722, 2026). "As little under half of BRAF class 3 colorectal cancers in our analysis carry additional pathogenic Ras pathway mutations, we speculate that the efficacy of anti-EGFR therapy in this subset of double-mutant patients may be diminished." (PMID 39751654, 2025). "For instance, serial ctDNA monitoring for anti-EGFR resistance mutations identified colorectal cancer patients who benefited from rechallenge with anti-EGFR therapy, with one-third of patients lacking detectable circulating resistance variants showing further responses upon rechallenge." (PMID 39934875, 2025). "Recent evidence has demonstrated the advantages of using BRAF-targeted therapies, either alone or in combination with MEK inhibition and epidermal growth factor receptor-targeted treatment, in patients diagnosed with advanced colorectal cancer carrying the BRAF V600E mutation." (PMID 40731762, 2025). "Moreover, heightened EGFR expression in colorectal cancer cells has been linked to the activation of the AP-1 transcription factor, a key regulator of cancer proliferation and metastasis." (PMID 40787199, 2025). "The overexpression of EGFR has been implicated in the development of colorectal cancer." (PMID 40906195, 2025). "On the other hand, EGFR mutations S464L, G465R, K467T, and S492R observed in cetuximab resistance in colorectal cancer treatment are located at the contacting residues of tipranavir and indinavir while I491M is also a contacting residue of indinavir in our study." (PMID 38216592, 2024). "Additionally, mutational variants of EGFR, KRAS, and PIK3CA genes are identified by CTCs sequencing in patients with colorectal cancer, which are associated with therapeutic response to EGFR-targeted therapy in patients." (PMID 40026568, 2024).
colorectal cancer (continued). "Recent evidence suggests that patients with left-sided colorectal cancer are associated with favorable clinical benefits from anti-EGFR antibodies as a first-line treatment, and that those with right-sided colorectal cancer are associated with worse clinical benefits." (PMID 38862615, 2024). "Notably, a study of the use of EGFR inhibitors in colorectal cancer tumors with mutations and sotorasib resistance found that upregulation of EGFR was a common resistance mechanism, and dual targeting of EGFR and KRAS blocked acquisition of resistance." (PMID 38639476, 2024). "Patients from the Middle Eastern population with colorectal cancer had an EGFR mutation rate of 0%." (PMID 37296986, 2023). "Impact of EGFR mutation on prognosis of colorectal cancer is questionable." (PMID 37260182, 2023). "For example, we recently used a mathematical model to identify the mechanism that explains why colorectal cancer patients with a KRAS G13D mutation benefit from treatment with EGFR inhibitors despite KRAS mutations more commonly causing resistance to EGFR inhibitors." (PMID 37823369, 2023). "Although this technology was developed in 1994, the first human mAb based on transgenic mice technology (i.e., panitumumab) was only approved by the FDA and EMA in 2006 and 2007, respectively, to treat patients with colorectal cancer harboring epidermal growth factor receptor (EGFR) mutations." (PMID 36836166, 2023). "However, evidence shows that high MIG6 levels are associated with resistance mechanisms in colorectal cancer and EGFR-mutated NSCLC." (PMID 37917191, 2023). "NF1-mutant colorectal cancer cell lines are resistant to EGFR inhibitors, indicating that loss of NF-1 could be a biomarker for assessing the application of EGFR inhibitors." (PMID 38084101, 2023). "For example, the predominate type I enzyme PRMT1 methylates epidermal growth factor receptor (EGFR) to promote colorectal tumor growth in a xenograft model, and high EGFR methylation is associated with resistance to cetuximab treatment and reduced overall survival in patients with colorectal cancer." (PMID 36475791, 2022). "In addition, KRAS gene mutation indicates poor response of colorectal cancer patients to anti-EGFR targeted therapy." (PMID 36544770, 2022). "Additionally, we found that the other EGFR-positive KRAS mutations colorectal cancer, SW620(G12V), and HCT116(G13D), cell viability was affected by R9VH36 treatment." (PMID 35578244, 2022). "The current study investigated the relationship between risk factors for anti-EGFR antibody drug-induced acneiform rash and survival probability in colorectal cancer patients, as well as effects of drug withdrawal, dose reduction, or treatment discontinuation on treatment continuation." (PMID 36045384, 2022). "Conversely, when the presence of a variant allele is contraindicative for therapy (e.g., KRAS variant positivity and anti-EGFR treatment in colorectal cancer), variant-enriched expression may negatively impact treatment outcomes." (PMID 36675685, 2022). "However, some reports suggest that KRAS G13D mutant colorectal cancer is associated with an improved outcome after treatment with the anti-EGFR antibody cetuximab compared to responses observed for other KRAS mutations." (PMID 34680229, 2021). "Among these patients, one with NSCLC and one with colorectal cancer might lose the chance of treatment with cetuximab or panitumumab despite also carrying EGFR mutations." (PMID 34658138, 2021). "However, most patients withKRAScodons 12/13 wild-type colorectal cancer still fail to respond to anti-EGFR therapy, suggesting the involvement of other mutations." (PMID 32892548, 2021). "Additionally, loss of Bim or its expression in melanoma, colorectal cancer, intrahepatic cholangiocarcinoma, and EGFR-positive NSCLC is associated with worse prognoses." (PMID 34955827, 2021). "RARA and EGFR were associated with worse survival in colorectal cancer patients." (PMID 31896739, 2020).